IRAK1 (interleukin 1 receptor associated kinase 1)
Diseases named in the same sentence as IRAK1 in open-access papers (continued):
Sharing a sentence is not in itself a finding about the gene and the disease.
HCMV infection (1 paper, 2015). "In this study we demonstrate that in addition to MICB and the secretome pathway, HCMV miR-UL112-3p modulates the TLR/IRAK1/NFκB signaling pathway by targeting TLR2, a HCMV sensor that plays an important role in mammalian control of CMV infection." (PMID 25955717, 2015).
hepatitis C virus infection (1 paper, 2016). A viral infection caused by the hepatitis C virus. "In addition, miR-21 is upregulated during hepatitis C virus infection and negatively regulates IFN-α signaling through MyD88 and IRAK1; it may thus be a potential therapeutic target for antiviral intervention." (PMID 27213347, 2016).
HIV-1 infection (1 paper, 2020). The type species of lentivirus and the etiologic agent of acquired immunodeficiency syndrome (AIDS). "IRAK1 protein expression levels were also decreased following HIV-1 infection." (PMID 32117283, 2020).
hypoxic ischemic encephalopathy (1 paper, 2024). "In addition, miR-146b-5p overexpression alleviates neonatal hypoxic ischemic encephalopathy-induced neuronal injury by inhibiting the IRAK1/TRAF6/TAK1/NF-κB pathway." (PMID 38533381, 2024).
immune deficiencies (1 paper, 2020).
immune thrombocytopenia (1 paper, 2023). "Bone marrow mesenchymal stem cell-derived exosomes induce the Th17/Treg imbalance in immune thrombocytopenia through miR-146a-5p/IRAK1 axis." (PMID 36980827, 2023).
Intellectual disability (1 paper, 2017).
interstitial lung disease (1 paper, 2025). A diverse group of lung diseases that affect the lung parenchyma. "Patients harbouring IRAK1 variants exhibited more severe clinical manifestations, including diffuse cutaneous lesions and interstitial lung disease, consistent with earlier findings linking IRAK1 polymorphisms to enhanced disease activity and fibrosis pathways in SSc." (PMID 41283471, 2025).
invasive candidiasis (1 paper, 2015). "MiR-155 miRNA is down-regulated in individuals infected with invasive candidiasis, and cytokine is a target protein that is involved in inflammatory signaling including IRAK1, Traf6 and Myd88." (PMID 26313489, 2015).
irritable bowel syndrome (1 paper, 2021). Irritable bowel syndrome (IBS) is a chronic functional condition of the lower gastrointestinal (GI) tract characterized by abdominal pain or discomfort and disordered bowel habit (diarrhea, constipation, or fluctuation between the two). "The purpose was to analyze the effect of sodium butyrate on IRAK1 at the cellular level and explore the effect of sodium butyrate on IRAK1 protein expression and visceral sensitivity in the colon of irritable bowel syndrome." (PMID 33906562, 2021). "The effect of sodium butyrate on IRAK1 protein expression and visceral sensitivity in the colon of irritable bowel syndrome is explored." (PMID 33906562, 2021).
leishmaniasis (1 paper, 2023). Infectious disease that is transmitted through the bite of hematophagous female phlebotomine sand flies. "KEGG pathway analysis revealed their involvement in Yersinia infection, Leishmaniasis, and Pertussis, while Reactome pathways primarily included p75NTR recruitment of signaling complexes, NF-kB activation and survival signaling, and IRAK1 recruitment of the IKK complex." (PMID 38025715, 2023).
Miscarriage (1 paper, 2025). A pregnancy that ends at a stage in which the fetus is incapable of surviving on its own, defined as the spontaneous loss of a fetus before the 22th week of pregnancy. "Furthermore, it has been reported that miR-146b-5p suppresses trophoblast proliferation and implantation-associated inflammation via inhibiting IRAK1 expression, which results in miscarriage in humans." (PMID 40218311, 2025).
Multiple Organ Failure (1 paper, 2020). A progressive condition usually characterized by combined failure of several organs such as the lungs, liver, kidney, along with some clotting mechanisms, usually postinjury or postoperative. "The IRAK-1 protein has several alleles, and one of the less common variants was associated with a higher risk of developing multiple organ failure and mortality in trauma or septic patients." (PMID 32948079, 2020).
myasthenia gravis (1 paper, 2023). Myasthenia gravis (MG) is a rare, clinically heterogeneous, autoimmune disorder of the neuromuscular junction characterized by fatigable weakness of voluntary muscles. "In myasthenia gravis (MG), miR-146a is downregulated and negatively correlated with levels of messenger RNA (mRNA) such as interleukin-1 receptor-related kinase 1 (IRAK1), tumor necrosis factor (TNF) receptor-related factor 6 (TRAF6), and inducible T cell costimulator factor (ICOS)." (PMID 38058356, 2023).
neuroborreliosis (1 paper, 2023). "Interestingly, a recent in vitro study of neuroborreliosis, using human brain microvascular endothelial cells challenged with Borrelia bavariensis, also showed an upregulation of IRAK2 and MYD88, while no significant changes were detected for IRAK1 or TRAF6 expression." (PMID 37319241, 2023).
neuromyelitis optica spectrum disorder (1 paper, 2021). "However, there was little study about the correlation of IRAK1 functional single nucleotide polymorphisms with mRNA expression in neuromyelitis optica spectrum disorder (NMOSD) patients." (PMID 34531808, 2021).
neuropathy (1 paper, 2017). A disorder affecting the nervous system that manifests with pain, tingling, numbness, and/or muscle weakness. "IRAK1 is down regulated (FC = 0.008) in skeletal muscle tissues of T2DM patients and it is associated with neuropathy." (PMID 28761062, 2017).
oral squamous cell carcinoma (1 paper, 2015). "Interestingly, tumor suppressive functions of IRAK1 have been proposed in a recent publication in oral squamous cell carcinoma cells (OSCC)." (PMID 26527316, 2015).
ovarian serous cystadenocarcinoma (1 paper, 2024). A malignant serous cystic epithelial neoplasm arising from the ovary. "IRAK1 was highly expressed across most samples analyzed in the Firehose Legacy dataset, comprised of 617 ovarian serous cystadenocarcinoma samples." (PMID 38796478, 2024).
ovarian tumor (1 paper, 2013). "We report three genes (IRAK1, CHEK1 and BUB1) to be significant in ovarian tumor samples for the first time, to the best of our knowledge." (PMID 23383610, 2013).
papillary thyroid carcinoma (1 paper, 2015). "The influenced genes by miR-146a include IL-1 receptor-associated kinase 1 (IRAK1), TNF receptor-associated factor 6 (TRAF6), and papillary thyroid carcinoma 1 (PTC1)." (PMID 25983750, 2015).
peritoneal disease (1 paper, 2024). "IRAK1 Scr or IRAK1 KD A1847 cells were injected intraperitoneally (IP) in NOD-scid IL2Rγnull (NSG) mice to replicate advanced peritoneal disease of HGSOC." (PMID 38796478, 2024). "Knockdown of IRAK1 impaired tumor growth in peritoneal disease models, and impaired HA-induced spheroid growth and STAT3 phosphorylation." (PMID 38796478, 2024).
prostate (1 paper, 2023). "Targeting IRAK1 signaling in PCa and other prostate pathologies comes with multiple benefits in impeding chronic inflammatory effects and also dampening the tumorigenic activities of the NF-κB transcriptional factors downstream of IRAK1 in the inflammatory cascade." (PMID 37370720, 2023).
prostate tumor (1 paper, 2022). "By analyzing bulk RNA-seq data from TCGA using ebayes for differential expression, we found that IRAK1 was significantly overexpressed in prostate tumor tissue (TU) compared to normal prostate tissue (TU, N=341; NOR, N=35; Benjamini-Hochberg adjusted p<2x10-8)." (PMID 36226067, 2022).
psychosis (1 paper, 2021). "A secondary network analysis of significantly altered focus and reference proteins associated the IL-1 receptor with SERPINA3, GABRG2, GAD2, and IRAK1 with schizophrenia and related disorders (early-onset schizophrenia, schizoaffective disorder, and psychosis)." (PMID 33976392, 2021).
pterygium (1 paper, 2023). A wedge-shaped fibrovascular lesion arising from the bulbar conjunctiva and extending to the cornea. "Several DEGs in pterygium and pSS tissues were identified from the datasets, and five hub genes (IL1R1, ICAM1, IRAK1, S100A9, and S100A8) were finally screened out." (PMID 36768371, 2023). "Compared with the healthy control conjunctiva, the expression of five hub genes (IL1R1, ICAM1, IRAK1, S100A9, and S100A8) in pterygium or pSS samples was statistically significant (p < 0.05)." (PMID 36768371, 2023). "We identified a shared gene signature (IL1R1, ICAM1, IRAK1, S100A9, and S100A8) between pterygium presence and pSS." (PMID 36768371, 2023).
sarcoidosis (1 paper, 2020). Sarcoidosis is a multisystemic disorder of unknown cause characterized by the formation of immune granulomas in involved organs. "For example, mTORC1 activation of macrophages has been associated with disease progression, and alveolar macrophages from sarcoidosis patients have upregulation of interleukin-1 receptor associated kinases (IRAK1 and IRAK-M) and receptor interacting protein 2 (Rip2)." (PMID 33329511, 2020).
sarcopenia (1 paper, 2025). Progressive decline in muscle mass due to aging which results in decreased functional capacity of muscles. "Upregulation of miR-126-5p has demonstrated high diagnostic accuracy for sarcopenia, while miR-146a upregulation contributes to sarcopenia by modulating the IRAK1/TRAF6/NF-κB signaling pathway." (PMID 40678078, 2025).
scleroderma (1 paper, 2020). Scleroderma is a rare autoimmune connective tissue disorder characterized by abnormal hardening of the skin and, sometimes, other organs. "The possible attribution of IRAK-1 in the pathogenesis of scleroderma, comes from the study in which inherited IRAK-1 deficiency in a boy resulted in the poor responses of his fibroblasts to the TLRs agonist." (PMID 33297945, 2020).
serous ovarian adenocarcinoma (1 paper, 2024). "In mining the Firehose Legacy serous ovarian adenocarcinoma dataset, we also identified that IRAK1 CNA was mutually exclusive from patients with BRCA and DNA damage-related repair gene mutations, defining a possible subset of EOC patients (~25%) that may respond to TIR targeted therapies." (PMID 38796478, 2024).
Sjögren’s syndrome (1 paper, 2025). "While some immune-cell studies suggest a pathogenic function in Sjögren’s syndrome, epithelial studies show anti-inflammatory effects via targeting IRAK1." (PMID 41516297, 2025).
temporal lobe epilepsy (1 paper, 2022). A localization-related (focal) form of epilepsy characterized by recurrent seizures that arise from foci within the temporal lobe, most commonly from its mesial aspect. "Yan found that the brain tissue of patients with refractory temporal lobe epilepsy had higher IRAK1 expression than that of normal control group." (PMID 34969353, 2022).
Urethral stricture (1 paper, 2025). Narrowing of the urethra associated with inflammation or scar tissue. "In a rat urethral fibrosis model induced by TGF-β1, miR-146a-enriched exosomes derived from TNF-α-treated HUMSC suppressed urethral stricture by reduction of IL-1β/-6, IL-1 receptor-associated kinase 1 (IRAK1), TNF receptor-associated factor 6 (TRAF6), and NF-κB levels in target cells." (PMID 40676634, 2025).
VEXAS syndrome (1 paper, 2026). An adult-onset inflammatory disease that affects only males and is caused by somatic, not germline, mutations. "Pacritinib, an oral inhibitor of IRAK1, JAK2, and ACVR1, has emerged as a promising therapeutic option for VEXAS syndrome." (PMID 41753113, 2026).
Zinc deficiency (1 paper, 2017). A deficiency of the essential metal Zinc; an essential cofactor for many enzymes. "One can speculate, that inactivation of zinc-containing metalloproteases during zinc deficiency, prevents the destruction of IRAK1, which remains to be investigated." (PMID 29064429, 2017). "Interestingly, phosphorylation and ubiquitination of IRAK1 was not affected by zinc deficiency, at least not early after stimulation, suggesting a selective effect of zinc on certain signaling pathways, shortly after LPS-stimulation." (PMID 29064429, 2017).
tumor (91 papers, 2013 to 2026). "IRAK1 has been implicated in various malignancies, contributing to tumor progression, metastases formation, and treatment resistance." (PMID 39451208, 2024). "High IRAK1 expression was associated with large tumor size, metastasis, advanced T status, and poorer overall survival (OS) in HCC patients." (PMID 37108068, 2023). "Interleukin 1 Receptor Associated Kinase 1 (IRAK1) is serine/threonine kinase implicated in the NF-kB-regulated inflammatory response, antiapoptosis, and tumor development." (PMID 35264191, 2022). "IRAK1 has a well-established role in innate immunity and inflammation and has been implicated in many types of neoplasia, as well as other diseases." (PMID 34906138, 2021). "Studies suggest that TRAF6, IRAK1 andEGFR, a protein associated with tumour progression andmetastasis, are targets for mir146a-5p." (PMID 32142098, 2020). "This review also covers the significance of IRAK1 in mediating cancer resistance to therapy and the underlying molecular mechanisms, including the evasion of apoptosis and maintenance of an inflammatory tumor microenvironment." (PMID 39451208, 2024). "High expression of IRAK1 was also observed in many endometrial cancer patients and found to be positively correlated with poor prognosis, higher tumor metastasis, myometrial invasion, and tumor-associated deaths." (PMID 37370720, 2023). "Other publications define miR-146a as tumor suppressive, where its loss hyper-activates IRAK1 and may be one mechanism for IRAK1 overexpression." (PMID 26527316, 2015). "Furthermore, exosomes released by non-small cell lung cancer cells inhibit the expression of TNF receptor-associated factor 6 (TRAF6) and interleukin-1 receptor-associated kinase (IRAK1) in M0 macrophages, impairing M1 polarization and diminishing their ability to eliminate tumor cells." (PMID 38655063, 2024). "Underexpression of miRNA-192-5p in M2-sEVs significantly restricts tumor formation, while the expression of its downstream target, the catalytically active protein kinase interleukin 1 receptor (IL-1R)-associated kinase 1 (IRAK1), is positively correlated with cancer progression." (PMID 35832790, 2022). "Upregulation of IRAK1 was also observed in carboplatin resistant tumor tissue compared to the sensitive tissue of OvCa patients and A2780 cells exhibiting platinum resistance." (PMID 38796478, 2024). "Similar findings reported that miR-146a, through the inhibition of IRAK1, retards tumor progression in lung adenocarcinoma cells, and the invasive potential of cervical and colorectal cancer (CRC) cells." (PMID 39451208, 2024). "The researchers identified amplification as the most common DNA alteration, likely contributing to the high IRAK1 expression observed in tumor tissues." (PMID 39451208, 2024). "One of the mechanisms by which IRAK1 facilitates tumor migration and invasion is through the regulation of the EMT process." (PMID 39451208, 2024). "The activation of the TLR/IL-1R axis triggers IRAK1 propagating downstream NF-κB activation and the subsequent expression of various pro-angiogenic factors essential for tumor growth and metastasis such as VEGF, CXCL1, and IL-8." (PMID 39451208, 2024). "Tumor tissue exhibited significantly higher IRAK1 protein expression compared to normal fallopian tubes, as determined by a board-certified pathologist." (PMID 38796478, 2024). "Expression of IRAK1 was then determined in normal tissue (Ctrl), primary tumor (PT), and recurrent tumor (RT) samples." (PMID 38796478, 2024). "Mice injected with IRAK1 Scr cells developed extensive peritoneal tumor growth and malignant ascites in 5/5 mice." (PMID 38796478, 2024). "Overexpressed in several cancers, IRAK1 is a therapeutic target, whose inhibition impairs tumor growth and metastasis." (PMID 38637555, 2024). "In vivo, miR-192-5p overexpression in TAM-derived exosomes inhibit IRAK1 and NF-κB expression in tumor tissues and downregulated NF-κB phosphorylation." (PMID 38792088, 2024).